IL6 (interleukin 6)
Diseases named in the same sentence as IL6 in open-access papers (continued):
Sharing a sentence is not in itself a finding about the gene and the disease.
infection (continued). "Respiratory viruses cause significant changes in the levels of cytokines or chemokines such as IL-6, MCP-1, and IP-10 during infection." (PMID 36249527, 2022). "We recently observed that infection with either attenuated (NH/P68) or virulent (22653/14) ASFV resulted in moMφ impaired ability to release IL-12, IL-6, and TNF-α in response to stimulation with IFNγ and LPS or a TLR2 agonist." (PMID 35215216, 2022). "Across in ovo treatment, the expressions of IL-2, IL-6, IL-10, TGF-β4, TLR-4, 1α-hydroxylase, and VDR were significantly higher at 2 wk post-infection (28 doa) in comparison to their expression levels before coccidiosis infection (14 doa)." (PMID 36230268, 2022). "A strong interaction between dietary APS and NE infection was observed in relation to TLR2, IFN-γ, TNF-α, IL-6, IL-10, RORα and Foxp3 (P < 0.05) in jejunum." (PMID 35265068, 2022). "Mean concentrations of IL-6, IL-1β, and TNF-α pre infection were 0.69 ± 0.27 pg/mL, 0.07 ± 0.03 pg/mL, and 0.32 ± 0.06 pg/mL (mean ± SE), respectively." (PMID 35281029, 2022). "Consistently, the gene expression of Ifnb1, Il6, Cxcl10, and many ISGs was also reduced in BX795-pretreated cells during infection." (PMID 35604097, 2022). "Analysis of the serum of P+ participants also revealed increases in IL-1Ra, IL-6, IFN-γ and IL-18, with the greatest differences observed at 72 h, consistent with a delay in the kinetics of the immune response from the site of infection to the blood." (PMID 35140232, 2022). "Treatment with DI resulted in a modest reduction of HA expression early in infection and a marked reduction of CXCL10, IL6, and IFNB expression." (PMID 35025971, 2022). "After the adjustment of operating time and intraoperative hypotension, levels of IL-6 (Prep, POD1, POD2), IL-12 (POD1, POD2), IL-18 (POD1, POD2), and IL-8 (POD2) were found to be correlated with postoperative infection outcomes (p < 0.05)." (PMID 36299462, 2022). "In part, this is attributed to the capacity of low physiological levels of estrogen to stimulate the production of the acute inflammatory cytokines interleukin-6 (IL-6) and tumor necrosis factor (TNF), which are active in infection control." (PMID 36273184, 2022). "The level of IL-6 was comparable between the untreated and 40 mM L-GSH-treated animals at 2 weeks post-infection, although treatment with 80 mM L-GSH significantly reduced the IL-6 levels." (PMID 35453358, 2022). "High levels of TNF-α, IL-6, IFN-γ, and IL-1β cytokines were induced in the lung samples from naïve mice at 6 days after infection." (PMID 36146461, 2022). "Expression of pro-inflammatory cytokines interleukin-6 (IL-6) and tumor necrosis factor-α (TNF-α) in ZIKV spleen at both mid and late disease was two-fold to three-fold higher than pre-infection." (PMID 35876869, 2022). "Compared to the control group, chickens in the M group had increased IL-6, IFN-γ, IL-1β, and IL-10 mRNA expression on days 4, 7, and 10 post-infection (p < 0.05)." (PMID 35875532, 2022). "We next quantified the gene expression of IL-6 and CCL-2 in the lungs of K18-hACE2 mice at day 3 after infection." (PMID 35746611, 2022). "These evidences suggest that IL-10, IL-6, IL-8, TNF-β, and IFN-γ are all abnormally expressed in infection." (PMID 35463642, 2022). "The protein levels of IL-1β, IL-6, and IFN-β were highest after infection of 12 h, but TNF-α was maintained in the higher levels after 24 h." (PMID 35458442, 2022). "Probing for SARS-CoV2, we see significant increases with infection of SARS-CoV-2, which is similar to the results from combination with IL-6 and IL-1β (ILs)." (PMID 34669512, 2022). "Previous studies have shown significantly higher concentrations of IFNα, IL-2, IL-6, IL-12p70, CXCL10, and GM-CSF in patients with a clinical diagnosis of prolonged post-infection fatigue (>6 months) reporting a history of symptomatic WNV infection." (PMID 35458486, 2022).
infection (continued). "Since there are presently no recognized and accepted biomarkers for assessing SCI levels alone, SCI is usually measured by combining the clinical biomarkers of acute inflammation and infection, such as CRP, IL-6, and TNF-α." (PMID 36556207, 2022). "In order to evaluate the influences of CRKP colonization and translocated infection on inflammatory factor expression, interleukin-1β (IL-1β), tumor necrosis factor alpha (TNF-α), IL-6, and IL-10 concentrations were analyzed." (PMID 36445086, 2022). "ELISA assay revealed consistent results with the qRT-PCR assay, suggesting that dTHP1 cells secreted large amounts of proinflammatory cytokines (IL-6, IL-1β, and TNF-α) and chemokine MCP-1 into the supernatant during the infection process (p < 0.05)." (PMID 35359716, 2022). "We found the levels of CXCL1, IL-6, IL-1β, CCL3 and CCL4 were higher in the kidney homogenates of female mice infected with the eng1 strain at days 1 and 4 post-infection in comparison to that infected with the ENG1 strain." (PMID 34995333, 2022). "Bacteria burdens, neutrophil recruitment, and activation (CD11b expression, myeloperoxidase, and elastase levels), interleukin (IL)-1β, IL-6, and tumor necrosis factor (TNF) were measured in bronchoalveolar lavage fluid (BALF) at 6 and 24 h after infection." (PMID 35269409, 2022). "BALF levels of the proinflammatory cytokines IL-1β, IL-6, and TNF were similar in both mouse strains at 6 h after infection." (PMID 35269409, 2022). "Our data suggest that NP is produced at the early phase of infection by different signaling pathways and/or cells from those of CRP and IL-6." (PMID 35529699, 2022). "Subsequently, the regulation of the immune response to infection adjusts the expression of inflammatory factors, including iNOS, COX-2, IL-6, IL-1β, and TNF-α." (PMID 35159514, 2022). "A very high value of IL6 was found for NN1 in contrast to NN2, which confirms the severity of infection in NN1 (3335 vs. 760 pg/mL)." (PMID 36143827, 2022). "We then measured the expression of inflammatory cytokines such as IL-6, IL-8, and TNF-α in BMECs after infection with M. bovis under different strains and at different MOIs." (PMID 35464378, 2022). "TNF-α, IL-6, and INF-γ’s Levels in the serum of MafK Tg mice were all significantly upregulated compared to WT mice following a 2 day infection with Salmonella." (PMID 35260530, 2022). "There was some literature suggesting that IL-6 rises earlier than PCT and CRP after the onset of infection, which also correlates with the severity of the infection." (PMID 35794529, 2022). "To examine IL-6, IL-1β, IFN-γ, and TNF-α mRNA expression in mice lungs following infection with EHV-8, we inoculated BALB/c mice with EHV-8 and analyzed them by qPCR." (PMID 36230234, 2022). "We observed that after sixteen hours of infection monocytes produced a significant amount of IL-1β, TNF-α, IL-6 and IL-10 in response to viable fungal spores." (PMID 36311802, 2022). "The IL6 and vitamin D levels, together with ABG markers, were the keys used to predict the course of the infection." (PMID 36428884, 2022). "In order to investigate role of this receptor in the HAdV26-induced expression of IL-6 and TNF-α, we downregulated the amount of αvβ3 integrin by using specific siRNA in SK-OV-3 cells prior to HAdV26 infection." (PMID 35458402, 2022). "In terms of infection index, PCT showed a significant decrease after treatment (48.79%), while the IL-6 decrease was more obvious (81.80%)." (PMID 36249210, 2022). "Transcripts encoding cytokines and chemokines such as IL-1β (interleukin-1β), IL-18, IL-6, IFN-γ, IL-10, CCL2 (C-C motif chemokine ligand 2), CCL4 and CCL7 were also up-regulated in the lungs during infection." (PMID 34965194, 2022).
infection (continued). "Increased cytokines and chemokines such as IL-6, GM-CSF, IL-1a, IL-15, CXCL9 and CXCL10 and complement system components such as C3 were also observed from 6 to 36 months after infection in patients with chronic disease compared to with retrieved controls." (PMID 36189282, 2022). "Further, ALI exposed epithelial cells showed the upregulation of IL-6, IL-8, and IP-10, along will eotaxin-1 and VEGF-A after infection with HNDV." (PMID 36071442, 2022). "Macrophages actively participate in inflammatory responses by releasing pro-inflammatory cytokines: TNF-α, IL-1β, and IL-6 as well as inflammatory cytokines such as NO and PGE2 and recruit additional immune cells to the site of infection or tissue injury." (PMID 35743169, 2022). "Upon infection with JEV, astrocytes release vascular endothelial growth factor (VEGF), IL-6, and MMPs." (PMID 35615063, 2022). "Infection with SARS-CoV-2 mediates inflammatory cytokines and chemokines, where ATII-induced interleukin-6 (IL-6) synthesis usually requires NOX-derived ROS." (PMID 35639261, 2022). "Infection with both bacteria and DP1 antagonists significantly reduced the mRNA expression and secretion levels of IL-6, IL-1β, and TNF-α compared with those in the bacteria-only group (P < 0.05)." (PMID 36435808, 2022). "Proinflammatory cytokines and chemokines analyses in the BAL showed that VACV∆C7L infection resulted in the release of IFN-γ, IL-6, CCL2, CXCL10, and CXCL9 into the BAL." (PMID 35351885, 2022). "Cells were harvested at 10 hr after infection, and the mRNA levels of IL8, IL6, and IL1β were measured by qRT-PCR." (PMID 35762728, 2022). "In vitro, infection of Vero-E6 cells with SARS-CoV-2 induced senescence (SenTraGor), DNA damage (γ-H2AX) and increased cytokine (IL-1β, IL-6, CXCL8) and apolipoprotein B mRNA-editing (APOBEC) enzyme expression." (PMID 35086840, 2022). "In response to ocular HSV-1 infection, pro-inflammatory cytokines including IL-1, IL-6 and chemokines including CCL2, CCL3, CCL5, CXCL1, CXCL2, CXCL9, and CXCL10 are produced rapidly following infection by resident cells and infiltrating leukocytes." (PMID 36685562, 2022). "The naïve infection control group showed the highest levels of TNF-α, IL-6, IFN-γ, and IL-1β cytokines in airway BALF and lung samples at 5 days after infection." (PMID 36146461, 2022). "IL-6 producing CD138+ cells were more frequent in SIVagm than SIVmac infection in the pLN, further suggesting that the loss of IgA in lumen in SIVmac infection could eventually be related to reduced levels of plasma cells, while these are maintained in SIVagm infection." (PMID 35798936, 2022). "For example, the brain side of the gNVU showed IFN-γ, IL-6 and IL12-p70 as upregulated cytokines, while the vascular side showed IL-1β and IL-8 as upregulated cytokines in the context of infection by VEEV-TC83." (PMID 36560802, 2022). "Cytokines including IL-1β, IL-6, IL-12 p40, IP-10, IFN-γ, and TNF-α were increased in S. enteritidis-infected mice at 4 days post-infection." (PMID 35222370, 2022). "The viability of E44 on HBMECs surface and intracellular of each group and IL-6 and TNF-α were used as indicators of invasion, adhesion, and inflammation after E44 infection." (PMID 36289622, 2022). "IL-6, IL-8, IL-1β, TNF-α, and IFN-γ are pro-inflammatory cytokines involved in promoting the acute inflammatory response and defending against infection." (PMID 36364088, 2022). "Like IL6, EN-RAGE is produced by macrophages and neutrophils as an antimicrobial response to infection or inflammation." (PMID 36167782, 2022). "We found cytokine responses secreted by ARPE-19 cells to be similar to the whole eye homogenate of the rat eyes, as secretion of IL-6, MCP-1 and GRO/KC was significantly increased following infection." (PMID 36194021, 2022). "IL-6 can induce the production of CRP and procalcitonin (PCT), which is directly related to inflammation and infection, facilitating the diagnosis of early inflammation and early warning of sepsis." (PMID 36506506, 2022).
infection (continued). "Upon infection with ZIKV, a release of IL-6 and TNF-α ensues, which has detrimental effects on the fetal brain." (PMID 36300375, 2022). "At 6 h post infection, SLPI KO mice did, however, have significantly higher BAL fluid levels of IL-6 than that of wild type mice." (PMID 36551159, 2022). "The results revealed that at the early stage of infection, TMUV inhibited LPS-induced IL6 production; the inhibition was roughly at similar level for 2, 4, and 12 h p.i. but was lost at 24 h p.i.." (PMID 36379254, 2022). "The unstimulated cytokine concentrations post-infection were within the reference range, and the concentrations of TNF-α and IL-6 were significantly lower post-infection than during antibiotic therapy." (PMID 35360000, 2022). "On the other hand, the expression levels of BCL2, CDKN2A, IL-6, and PPARA remained similar in both male and female mice after infection but were significantly upregulated in male mice after infection in combination with exogenous SP-A2 (1A0) protein." (PMID 35844510, 2022). "Our study has also revealed that after infection of RPE cells with parasites, mRNA expression of GM-CSF, IL-1β, IL-6 and IL-8 showed a statistical increase." (PMID 36171756, 2022). "Meanwhile, the mRNA levels of IL-6, IP-10, TNF-α, and IL-1-β were increased during reinfection but were lower than those during primary infection." (PMID 35893674, 2022). "Surprisingly, despite higher CFUs and neutrophils within C3aR−/− lungs and BALF, respectively, C3aR−/− and WT had the same level of inflammatory cytokines (IL-6, TNF, or IFNγ) within the BALF throughout the duration of infection." (PMID 35925892, 2022). "A cascade of biomolecular events occurs in an intricate network after exposure infection of SARS-COV-2 including the production of interleukins 1β, 6, 10 (IL-1β, IL-6, IL-10, MCP-1), and tumor necrosis factor-α (TNF-α)." (PMID 34463916, 2022). "In particular, laboratory parameters of infection such as C-reactive protein (CRP), procalcitonin (PCT) and interleukin 6 (IL-6) are able to provide valuable information on the presence and progression of infection." (PMID 35887994, 2022). "In responding to infection, T lymphocytes, monocytes, and neutrophils are recruited to infection sites and secrete various cytokines, such as TNF-α, IL-1, and IL-6." (PMID 36238276, 2022). "Human neutrophils also produce numerous different pro- and anti-inflammatory cytokines upon stimulation, such as TNF-α, IL-1β, IL-6 and IFN-γ, as well as a wide array of chemokines to recruit other immune cells to the site of infection." (PMID 36203565, 2022). "However, since rapamycin elevated viral ORF1A by 400-fold but only increased cellular IL6 and IFNB1 by 2.5-fold or less, these results suggest that rapamycin increased cellular susceptibility to SARS-CoV-2 infection, while limiting inflammatory cytokine induction in response to infection." (PMID 36264642, 2022). "The microorganism strongly triggered the secretion of the tested pro-inflammatory cyto- and chemokines IL-6, IL-8, and TNF-alpha, determined at 24 h post-infection." (PMID 36519178, 2022). "Upon PVM inoculation, a significant increase in IL-6 production was detected in mock-primed WT and CCR2−/− mice, starting at 12 h post infection and continuously increasing to the last measure applied 72 h post inoculation." (PMID 35062301, 2022). "Beyond that, the changes of inflammatory factors at different time points also found that the expression of IL-6, TNF-α, and IL-8 was increased in BMECs after M. bovis infection and showed a change dependent on infection time and MOIs." (PMID 35464378, 2022). "We designed this cohort study based on this prospective database to compare the accuracy of IL-6 detected within 48 h of onset with that of CRP for the prediction of SAP, organ failure (OF), PN, infected pancreatic necrosis (IPN), and mortality." (PMID 36467730, 2022).
infection (continued). "Infections with the B.1.1.7, B.1.351, B.1.617.2, and MA10 viruses resulted in >100-fold increases in IL-6 and CCL-2 mRNA expression." (PMID 35746611, 2022). "The plasma levels of IL-6, IL-1β, and TNF-α were higher in the untreated group than in the mock group on days 1, 3, and 5 post-infection." (PMID 36569095, 2022). "Deletion of 4b protein led to a significant reduction in the expression of IFNß, pro-inflammatory cytokines (IL-6 and IL-8) and chemokines (CCL2 and CXCL10) in relation to MERS-CoV-MA-WT infection." (PMID 36129908, 2022). "Adjuvanted vaccine groups showed lower levels of inflammatory cytokines (IL-6, IFN-γ, IL-1β) compared to the vaccine-only group or naïve mice after lethal infection." (PMID 36146461, 2022). "IL-6, CXCL8, and IL-10 mRNA expression induced by ASFV-ΔH240R infection was increased by approximately 5-, 5-, and 10-fold, respectively, compared with ASFV-WT." (PMID 34787458, 2022). "qPCR experiments indicated that poly(dA:dT)-induced transcription of IFNB1, IL6, and TNFA genes was impaired by pre-infection with ASFV, suggesting that ASFV has evolved strategies to antagonize the Pol-III-RIG-I axis." (PMID 35089988, 2022). "The differentially expressed cytokines such as IL6, IL10, IL11, IL15, TNFSF10, TNFRSF6B and TNFAIP6 were detected in the lung of goats after Pm infection in this study." (PMID 35739866, 2022). "Concordantly, pro-inflammatory mRNA induction (IL6, IL8, CCL2 and TNF) and cytokine release (CXCL10, IL6 and CCL5) were significantly lower after infection with Alpha, compared to first-wave isolates." (PMID 34942634, 2022). "In mice suffering from acute lung injury caused by lipopolysaccharide (LPS)-induced infection, a one-off CBD dose (20 mg/kg) administered prior to infection decreased the production of pro-inflammatory TNF, IL-6, MCP-1, and MIP-2." (PMID 35891472, 2022). "According to real-time PCR, the mRNA level of IL-1, IL-6, and TNF-α decreased significantly in KO mice compared with WT mice on Days 5 after infection." (PMID 35163412, 2022). "The IAV single-infection group showed a rapid increase in the levels of TNF-α, IL-1α, IL-6, and IFN-β from 2 dpi to 7 dpi." (PMID 35107382, 2022). "The expressions of IL-1β, IL-6, TNF-α, IFN-γ, IL-12, and CXCLi1 were also markedly increased in the livers of wild-type infected chickens on 5 days post-infection." (PMID 35694286, 2022). "During the early phase of infection (days 1–3 post-infection (p.i.)), the transcription of proinflammatory factors (i.e., IL-12, IFN-γ, TNF-α, IL-1β, IL-6, IL-18) was induced faster under BaP exposure." (PMID 35203386, 2022). "The levels of IL-2, IL-6, and TNF-α increased more than 80-fold upon infection with the ∆katG mutant." (PMID 35438052, 2022). "We observed a highly similar increase in IL-6 concentrations in the supernatants of LASV- and MOPV-infected cells 48 h after infection, but the change was only significant for MOPV." (PMID 35337059, 2022). "Gene expression analysis revealed a significant induction in pro-inflammatory cytokine transcription in keratinocytes during infection with S. aureus with induction of IL1A (p < 0.05), IL6 (p < 0.01), and CXCL8 (p < 0.05) at early time points." (PMID 34944618, 2021). "This bacteria stimulated immune cell responses (macrophages and dendritic cells derived from human monocytes) infected with these pathogens to reduce the infection by producing co-stimulatory and effector molecules (TNF-α, IL-6, IL-8, and iNOS)." (PMID 33919849, 2021). "The levels of IL-6, IL-8, HMGB-1, and IFN-β RNA transcripts increased in a time-dependent manner after infection." (PMID 33796483, 2021). "The percentages of IL-4+, IL-5+, IL-6+, IL-21+, IL-1α+, and IL-17+ γδT cells were increased (p < 0.05), but the percentage of IFN-γ-expressing γδT cells decreased (p < 0.05) post-infection." (PMID 33588839, 2021).